FGFR1 (fibroblast growth factor receptor 1)
Diseases named in the same sentence as FGFR1 in open-access papers (continued):
Sharing a sentence is not in itself a finding about the gene and the disease.
breast cancer (continued). "Breast cancer cells can develop metformin resistance by triggering IGF-1R target insulin receptor substrate-1 (IRS-1)/ERK signaling through overactivation of FGFR1; IRS-1 acts as a critical crosstalk mediator between IGF-1R and FGFR1 pathways, encompassing a feedback loop between IRS-1 and MAPK/ERK." (PMID 36017326, 2022). "In addition to FGFR1 overexpression, aberrant FGFR signaling in breast cancer may also include the amplification of FGFR1 and FGFR2, activation/mutations of FGFR2, increased secretion of FGF2, and other ligands from tumor microenvironment." (PMID 34831231, 2021). "They proved in both cells that dovitinib (also known as TKI 1258), which is an anti-FGFR1 antibody, was capable to reduce downstream signalling by a down modulation of pFRS2 and pERK/MAPK as shown by western blotting, and in vivo it reduced tumours in primary breast cancer xenografted HBCx-2 mice." (PMID 32188012, 2020). "Ross and coworkers have analyzed the most frequent copy number alterations that were observed in mucinous breast cancers and showed that: FGFR1 was more frequently amplified in mucinous than non-mucinous ER+ breast cancer (36% vs 11%); the FGF3/FGF4/FGF19 amplicon was frequently amplified (27%)." (PMID 32210163, 2020). "Also, no mutations were detected for other described breast cancer‐associated genes (e.g., RAD51, RAD50, p27, ESR1/2, ERBB2, ERBB3, AKT1, CCDN1, FGFR1, MYC, and RB1) in any of the tissues or the CTC cell line." (PMID 32667137, 2020). "Moreover, FGFR1 activation in breast tumor cells promoted the release of inflammatory chemokine CX3CL1, which in turn stimulated the migration of macrophages during the initial stages of mammary tumor formation." (PMID 33081025, 2020). "Results from our bioinformatics analysis of breast cancer patient samples and breast cancer cell line study revealed that FGFR1α and FGFR1β expression have distinct distributions across different groups, including FGFR1-amplified and non-amplified groups, and three subtype groups." (PMID 30713601, 2019). "To determine whether naturally occurring FGFR1 amplification promotes resistance to fulvestrant plus CDK4/6 inhibitors, we selected three ER+/HER2− human breast cancer cell lines with FGFR1 gene amplification as determined by FISH: CAMA1, MDA-MB-134, and HC150015." (PMID 30914635, 2019). "Among the genes consecutively upregulated by AP20187-activated iFGFR1, we were particularly interested in understanding how FGFR1 signaling regulates TNFAIP3 expression, since it plays an important role in NF-κB regulation but its role in breast cancer is unknown." (PMID 30111373, 2018). "Importantly, KO of TNFAIP3 inhibited tumor growth promoted by both mutant H-Ras and FGFR1 activation, suggesting that TNFAIP3 may serve as a potential target for inhibiting ER- breast cancer with active mutant Ras and/or active FGFR1 signaling." (PMID 30111373, 2018). "For example, it may be possible to target FGFR1 using antibody in strongly FGFR1-positive pancreatic cancer, in the same manner in which HER2 is targeted using anti-HER2 antibodies in HER2-positive breast cancer." (PMID 30593273, 2018). "In this paper, we have mentioned some genes may be used as potential targets for treating breast cancer including KLF6-SV1, CD44, VEGF121b, VEGF165b, VEGF-A, FGFR1, hnRNP A1, A2, I and hnRNP K. Among of them VEGF series variants have the more possibility to be used in the clinical practice." (PMID 28881705, 2017).
breast cancer (continued). "Moreover, lncRNA UCA1 contributes to progression of hepatocellular carcinoma through inhibition of miR-216b and activation of FGFR1/ERK signaling pathway and is upregulated in breast cancer, colorectal cancer, esophageal squamous cell carcinoma and bladder carcinoma." (PMID 28427159, 2017). "In this case, other genes located at the same locus may also be amplified and contribute to the oncogenesis of human mammary carcinomas, independent of FGFR1." (PMID 23900974, 2013). "We also treated mouse 4T1 breast cancer cells with shRNA lentiviral particles targeting FGFR1-3.The silencing efficiency was not as high as in S115 cells, but nevertheless FGFR2 and FGFR3 silencing also resulted in increased FGFR1 gene expression in these cells." (PMID 23185502, 2012). "Recent studies, however, have called into question the role of FGFR1 as the 'amplicon driver', given that not all cell lines and breast cancers with 8p11.2-p12 amplification overexpressed the FGFR1 gene and that FGFR1 protein and mRNA expression was much more pervasive than gene amplification." (PMID 17397528, 2007). "Furthermore, in breast cancer patients receiving radiochemotherapy (5-fluorouracil, vinorelbine, radiotherapy), FGFR1 expression correlated with good response to treatment, whereas FGFR1-negative cancers showed resistance to this treatment." (PMID 34830951, 2021). "Moreover, CCND1 amplification on 11q13 has been reported to be associated with luminal subtypes, and in agreement with this we found that CCND1 and FGFR1 amplification was most frequent in the luminal B subtype whereas CCND1 amplification was absent from all of the basal-like breast cancers." (PMID 22863309, 2012). "By comparing three-dimensional spheroid growth of ER + breast cancer cells with and without FGFR1 amplification, our research discovered that FGF2 treatment can paradoxically decrease proliferation in cells with FGFR1 amplification or overexpression." (PMID 38553760, 2024). "Together, these findings support that activation of the FGFR1 signaling mainly upregulates FOXQ1 expression and breast cancer cell proliferation through activating ERK2, but not ERK1, in the FGFR1-MEK-ERK2 signaling pathway." (PMID 36778115, 2023). "In preclinical studies, dovitinib showed the ability to inhibit FGFR1‐ and FGFR2‐amplified, but not FGFR‐normal breast cancer cell lines in vitro and inhibit tumour growth in FGFR1‐amplified breast cancer in vivo." (PMID 33655556, 2021). "In order to mimic this scenario in vitro, and to ascertain its functional role, we exposed 2 FGFR1-non-amplified (MCF7, T-47D) and 1 FGFR1-amplified (HCC1428) breast cancer cell line to prolonged hormonal deprivation (> 2 years)." (PMID 33579347, 2021). "However, despite the clear rationale for targeting FGFR1 in breast cancer with inhibitors, none have, to date, achieved an objective response, and this could be a consequence of inadequate patient selection and/or that FGFR1 may not be the only oncogenic driver in the 8p11-12 amplicon." (PMID 32517171, 2020). "When endogenous TGF-β was inhibited by a TGF-β receptor inhibitor, FGFR isoform switching and the regulation of FGFR1 and FGFR2 mRNA were not significantly altered in OSCC cells, in agreement with our previous observation in breast cancer cells." (PMID 31682640, 2019). "Preclinical data showed that dovitinib inhibits proliferation in FGFR1- and FGFR2- amplified, but not in FGFR-normal breast cancer cell lines." (PMID 26059247, 2015). "No studies analysing FGFR1 amplification, as defined by CISH, in a large cohort of breast cancer patients have so far been performed." (PMID 17397528, 2007). "A phase IIa study showed that patients with ER+ breast cancer who had progressed on aromatase inhibitors could benefit from the pan‐FGFR inhibitor AZD4547, regardless of their FGFR1 amplification status or expression levels." (PMID 38895905, 2024).
breast cancer (continued). "Interestingly, knockout of ERK2, but not ERK1, specifically suppressed the FGFR1 signaling-induced FOXQ1 expression and breast cancer cell proliferation." (PMID 36778115, 2023). "For example, FGFR1 amplification has been found in up to 20% of squamous non-small cell lung carcinomas (NSCLC), 18% of osteosarcomas, 10% of breast carcinomas, and 6% of small cell lung carcinomas, and was associated with sensitivity to FGFR inhibitors in preclinical in vivo models." (PMID 30326595, 2018). "Because the FOXQ1 gene is a protooncogene 25, 36, 37 that has not been studied in FGFR1-regulated cell growth, we aimed to investigate how FGFR1 signaling upregulates FOXQ1 expression and whether FOXQ1 is responsible for mediating breast cancer cell growth promoted by FGFR1 signaling." (PMID 36778115, 2023). "However, AXL silencing did not have any effect on the FGF2, VEGF-A, FGFR1, VEGFR1, and VEGFR2 expression of MDA-MB-231 breast cancer cells (data not shown), suggesting that AXL-mediated VM formation may be independent of the VEGF/VEGFR and FGF/FGFR axis." (PMID 33374832, 2020).
lung carcinoma (195 papers, 2007 to 2026). "The antiproliferative capacities of the Kallmann-associated Spry4 mutant exceed those of the corresponding wt, when expressed in DMS114, a lung cancer-derived cell line where FGFR1 amplification was identified as a driver mutation." (PMID 40806483, 2025). "While FGFR1 amplification has been well‐defined across multiple nonsmall cell lung cancer (NSCLC) datasets, the various FGFR fusion variants remain under‐characterized." (PMID 40242904, 2025). "Studies on lung cancer models have demonstrated that FGFR1 promotes cancer progression and is linked to risk factors for respiratory conditions like bronchiolitis and chronic inflammation." (PMID 39377013, 2024). "FGFR1 expression and/or amplification has been linked to epithelial-mesenchymal transition and metastasis in other cancers, including lung cancer, bladder and urothelial cancer, and gastric cancer." (PMID 37579831, 2023). "Compared to EGFR, however, bFGF and FGFR1/2 report few mutations, which therefore makes them potential reliable targets for lung cancer therapy." (PMID 37048074, 2023). "Intragenic FGFR1 rearrangements causing ectodomain-deficient FGFR1 were detected in 4 FGFR1-amplified lung cancer samples (8% of the FGFR1-amplified samples used in this study)." (PMID 37606995, 2023). "In this regard, studies in the literature report that bFGF and FGFR1 are associated with drug resistance in lung cancer." (PMID 37048074, 2023). "These ectodomain-deficient FGFR1 variants (ΔEC-FGFR1) were expressed in the affected tumors and were tumorigenic in both in vitro and in vivo models of lung cancer." (PMID 37606995, 2023). "We observed that PI3K and PTEN mutations were mutually exclusive with FGFR1-4EBP1 amplification in both breast and lung cancer, suggesting their redundant requirement." (PMID 35626002, 2022). "FGFR1 was found to mediate acquired resistance to trametinib in a panel of KRAS-mutated lung cancer cell lines in a shRNA screen targeting the human kinome." (PMID 34068816, 2021). "A similar mutation was observed for FGFR1 (FGFR1-V561M) in lung cancer, which drives resistance to AZD4547 through the activation of STAT3 and EMT." (PMID 34830951, 2021). "Overexpression of FGFR1 has previously been linked to shorter progress free survival (PFS) of lung cancer, and separately." (PMID 32380883, 2020). "In our study, we uncovered that a lipogenic switch underlies acquired ponatinib resistance of FGFR1‐driven lung cancer cells." (PMID 32064608, 2020). "Five of these variants were listed in dbSNP and two variants were identified as somatic variants in lung cancer (FGFR1 p.(Pro702Tyr)) or in a colon carcinoma ((GPT p.(Glu210Cys), COSMIC database;)." (PMID 31212687, 2019). "Recently, reactivation of MAPK pathway, mediated by NRAS amplification or MET transcriptional regulation, has been linked to the emergence of resistance to FGFR inhibitors in FGFR1-amplified lung cancer cell models." (PMID 30972293, 2019). "The malfunction in FGFR signaling (caused by mutations, gene rearrangements, gene multiplication and FGFR1 overexpression) has been observed in various malignancies such as breast, prostate and lung cancer." (PMID 30029518, 2018). "Similar to FGFR1 amplified lung cancer, it has also been associated with worse outcomes and strong association with tobacco and alcohol use." (PMID 29351293, 2018). "FP-1039 mediated tumor inhibition occurs more specifically in FGFR1-amplified lung cancer and FGFR2-mutated endometrial cancer." (PMID 27051190, 2016). "To investigate the associations between brachyury and FGFR in lung cancer, we measured brachyury and FGFR1-4 expressions in human lung tumor tissues and cells lines." (PMID 27893433, 2016). "Although fibroblast growth factor receptor 1 (FGFR1) has been implicated in activating TBXT expression in lung cancer through MAPK signaling, the genomic cis‐regulatory regions that mediate this activation are unknown." (PMID 40099944, 2025).
lung carcinoma (continued). "Frequencies of FGFR1–4 amplifications, mutations, and fusions in lung cancer." (PMID 35402233, 2022). "Failure of FGFR1 amplification as a predictive biomarker in lung cancer may be linked to expression of neighboring genes in the 8p11 amplicon." (PMID 35402233, 2022). "Conversely, RAS activation causes resistance to FGFR1 inhibitors in FGFR1-amplified lung cancers, suggesting that both FGFR1 and KRAS alterations can sustain aberrant MAPK pathway activation and drive reciprocal resistance to targeted drugs in lung cancer therapy." (PMID 34858498, 2021). "FGFR1 has been reported to cause resistance to MEK inhibitors in lung cancer cells." (PMID 34858498, 2021). "Further, Quintanal-Villalonga and his colleagues found that highly-expressed FGFR1 may result in a higher resistance to EGFR-TKI in the patients with EGFR-mutated lung cancer and those patients may benefit from combined EGFR/FGFR inhibition." (PMID 31998131, 2019). "Although the therapeutic benefits of FGFR1 inhibition in most FGFR1-activated lung cancers are well established, the mechanisms that cause AR remain largely unknown." (PMID 30140389, 2018). "Therefore, this study aimed to dissect molecular factors underlying acquired FGFR inhibitor resistance in FGFR1-driven lung cancer." (PMID 27367030, 2016). "Hence, we aimed at characterizing the molecular mechanisms underlying acquired nintedanib resistance in FGFR1-driven lung cancer." (PMID 27367030, 2016). "Lung squamous cell carcinoma represents 30% of lung cancers and only recently have possible drug-targetable mutations been identified in this disease, including fibroblast growth factor receptor 1 (FGFR1) gene amplification and genetic alterations in the phosphoinositide-3 kinase pathway." (PMID 27551478, 2015). "Furthermore, we compared FGFR1 amplification and expression to overall survival of patients and could not find a significant association in any of the tested histological lung cancer entities." (PMID 32207251, 2020). "However, FGFR1 expression is associated with unfavorable outcomes in other tumors, including lung cancer, triple-negative breast cancer, and gastric cancer, and FGFR1 may be a useful therapeutic target in these diseases." (PMID 26993773, 2016). "This engineered receptor fragment potently inhibits FGFR1-IIIc signaling in NCI-H1299 lung cancer cells by preventing FGF2-induced receptor activation." (PMID 41584352, 2026). "We present the screening and functional studies that identified FGFR1 activation as a feedback mechanism following KRAS G12C inhibition in lung cancer cells with a mesenchymal phenotype." (PMID 40788860, 2025). "The PLK1 gene was unraveled as a previously underappreciated therapeutic target whose loss of function is synthetically lethal with FGFR-targeted therapy in lung cancer with FGFR1 amplification." (PMID 40428391, 2025). "FGFR1 expression was typically elevated in mesenchymal lung cancer PDX models, and FGFR1 is a marker of EMT transition." (PMID 40788860, 2025). "Functional validation of these rare fusions by RNA-NGS showed that 4 of 5 intergenic-breakpoint fusions were validated, with 2 intergenic-FGFR1 fusions in lung cancer accounting for 50% of FGFR1-positive lung cases." (PMID 41092072, 2025). "For instance, FGFR3 fusions dominated in glioma (91.43%) and lung cancer (53.85%), while FGFR1 fusions were only observed in soft tissue sarcoma." (PMID 41092072, 2025). "In vivo, the OM-RCA-01 plus checkpoint inhibitor combination enhanced therapeutic efficacy in a patient-derived xenograft (PDX) lung cancer model overexpressing FGFR1." (PMID 40547805, 2025). "Previous research indicates the involvement of FGFR1 in activating TBXT expression in lung cancer via MAPK signaling, while a super‐enhancer downstream of TBXT is evident in chordoma." (PMID 40099944, 2025).